HOXA5 (homeobox A5)
Diseases named in the same sentence as HOXA5 in open-access papers (continued):
Sharing a sentence is not in itself a finding about the gene and the disease.
non-small cell lung carcinoma (20 papers, 2012 to 2024). A group of at least three distinct histological types of lung cancer, including non-small cell squamous cell carcinoma, adenocarcinoma, and large cell carcinoma. "In agreement, HOXA5 is also down-regulated in the vast majority of non-small cell lung cancer, which is associated with a borderline significantly worse survival in patients with stage I disease." (PMID 22227861, 2012). "Meta-analyses for the association of HOXA5 expression with survival of non-small cell lung cancer." (PMID 39121297, 2024). "In addition, HOXA5 expression was associated with better clinical outcome in non-small cell lung cancer patients with wild-type EGFR." (PMID 25875824, 2015). "In non-small cell lung cancer, HOXA5 was found to promote apoptosis and inhibit proliferation by upregulating linc00312 expression." (PMID 37812190, 2023). "Hoxa5 had been described to be involved in a number of different types of cancer, including small and non-small cell lung cancer, breast cancer, colorectal cancer, and so on." (PMID 35883405, 2022). "There have been several studies that reported the expression pattern of HOXA4 and HOXA5 in non-small cell lung cancer as well as the influence of HOXA4 and HOXA5 in biological behaviors of non-small cell lung cancer cells 10-13." (PMID 35370463, 2022). "Hoxa5 was served as tumor suppressor in a number of cancers including non-small cell lung cancer, osteosarcoma, gastric cancer and gastric cancer." (PMID 33014522, 2020). "Reduced HOXA5 expression is a biomarker for poor prognostic in human non-small cell lung cancer (NSCLC)." (PMID 29615582, 2016). "Hoxa5 was reported as downregulated in non-small cell lung cancer and could bind with the promoters of linc00312 to inhibit tumor proliferation." (PMID 35883405, 2022). "Previous studies indicated that HOXA5 could up-regulated linc00312 expression, and inhibit proliferation and promote apoptosis in non-small cell lung cancer." (PMID 32373208, 2020). "Two reports showed that HOXA5 gene expression is downregulated by aberrant promoter methylation in the vast majority of non-small-cell lung cancers (NSCLCs) and that it may play an important role in the carcinogenesis of NSCLCs." (PMID 25875824, 2015). "Therefore, targeted induction of HOXA5 may represent a promising approach for non-small-cell lung cancer therapy." (PMID 25875824, 2015). "Also, in non-small cell lung cancer (NSCLC) tissues, miR-196a was significantly upregulated, which in turn resulted in NSCLC cell migration and invasion, partially via downregulation of HOXA5, and miR-155 has been implicated in with inflammation and cardiovascular diseases." (PMID 38660676, 2024). "Overexpression of HOXA5 inhibited cell proliferation and invasion, and its expression level was significantly correlated with tumor-node-metastasis stages, tumor size, and LNM in non-small-cell lung carcinoma." (PMID 36454866, 2022). "HOX transcript antisense intergenic RNA (HOTAIR) is also correlated with the tumor stage and poor prognosis of non-small-cell lung cancer; the down-regulation of HOTAIR inhibits the invasion and metastasis of non-small-cell lung cancer cells through the down-regulation of HOXA5." (PMID 27527868, 2016).
colorectal cancer (17 papers, 2017 to 2025). A primary or metastatic malignant neoplasm that affects the colon or rectum. "Recently, HOXA5 hypermethylation has not only been associated with cancer as an aging-associated disease, but also with the age of colorectal cancer patients." (PMID 33547267, 2021). "Previously study has found that in colorectal cancer, HOXA5 is downregulated, and its re-expression can induce loss of the cancer stem cell phenotype, preventing tumor progression, and metastasis." (PMID 31165042, 2019). "HOXA5 can attenuate the growth and progression of cervical cancer and colorectal cancer by inhibiting the Wnt/β-catenin signaling." (PMID 36167790, 2022). "It has also been shown that Hoxa5 counteracts stem cell traits through inhibiting Wnt signaling in colorectal cancer." (PMID 35883405, 2022). "It has been noticed that this miRNA is overexpressed in colorectal cancer tissues compared to their normal counterparts and that miR-429 is able to augment EMT and metastasis of colorectal cancer by modulating the expression of homeobox A5 (HOXA5)." (PMID 33066509, 2020). "HOXA5 has also been reported to be down-regulated by miR-429, and promote colorectal cancer progression and metastasis." (PMID 32373208, 2020). "When HOXA5 short RNA levels were compared among colorectal cancer cells (HCT116, DLD1 and HT-29) and normal colonic epithelial cells (HCEC-1CT), it was determined that cancer cells expressed higher levels of HOXA5 short RNA than normal cells." (PMID 31159758, 2019). "Ordóñez-Morán found that HOXA5 is significantly downregulated and counteracts stem cell traits by inhibiting wnt signaling in colorectal cancer." (PMID 31165042, 2019). "Recently, a role in CSC regulation has been strongly established for HOXA5 in breast and colorectal cancer, whereby HOXA5 can maintain homeostasis by suppressing stemness in these tissues." (PMID 28202042, 2017). "Tumor cell lines (e.g., uterine, kidney, colorectal cancer) also showed elevated HOXA5 expression." (PMID 41209012, 2025). "HOXA5 is downregulated in colorectal cancer and prevents tumor progression and metastasis." (PMID 37845209, 2023). "All indicated promoter methylation may be responsible for the silencing of 3 HOXA genes in colorectal cancer, especially the HOXA5 and HOXA6." (PMID 31165042, 2019). "MiR-429 promoted tumor growth and metastasis in colorectal cancer by directly targetting HOXA5." (PMID 30042169, 2018). "Despite a lack of studies on methylation, HOXA5 has been implicated in colorectal cancer." (PMID 31165042, 2019). "In colorectal cancer, the percentage of methylation of three HOXA genes (HOXA5, HOXA2, and HOXA6) were up to 67.62%, 58.36%, and 31.32%, respectively." (PMID 36159969, 2022). "This indicated that hypermethylation of HOXA5, HOXA2, and HOXA6 is an important event in colorectal cancer." (PMID 31165042, 2019). "In this article, based on the latest colorectal cancer database and our experiments, we analyze the methylation status in three HOXA genes including HOXA2, HOXA5, and HOXA6 and its clinical application." (PMID 31165042, 2019). "HOXA5, HOXA2, and HOXA6 are frequently methylated, and this leads to silencing of these genes and progression of colorectal cancer." (PMID 31165042, 2019). "Notably, we found that the highest methylation of HOXA5 and HOXA2 occurs in early stage colorectal cancer tissues such as stage I and II, N0, MO, and non-invasive." (PMID 31165042, 2019). "Notably, we found that the highest methylation of HOXA5 and HOXA2 occurs in the early stages of colorectal cancer tissues such as stage I, N0, MO, and non-invasive tissues." (PMID 31165042, 2019). "Additionally, the correlation analysis in TCGA and our colorectal cancer tissues showed a significant negative correlation between methylation levels and the expression of HOXA5 and HOXA6 genes." (PMID 31165042, 2019).
colorectal cancer (continued). "Furthermore, the highest methylation of HOXA5 and HOXA2 was detected in the early stages of colorectal cancer including stage I, N0, MO, and no perineural invasion." (PMID 31165042, 2019).
leukemia (15 papers, 2007 to 2025). A malignant (clonal) hematologic disorder, involving hematopoietic stem cells and characterized by the presence of primitive or atypical myeloid or lymphoid cells in the bone marrow and the blood. "Functional analysis revealed that HOXA5 maintains leukemia through metabolic reprogramming (cholesterol biosynthesis) and ECM remodeling." (PMID 41209012, 2025). "Along with results from other studies that HOXA5 modulated cell cycle in Jurkat cells and hematopoietic stem cells, cervical cancer, mesenchymal stem cells, and leukemia cells." (PMID 34485110, 2021). "Even so, it is known that the HOXA10 gene has oncogenic potential in developing leukemia; specific roles of HOXA5, HOXA7, and HOXA10 in myeloid leukemias are poorly described." (PMID 31681584, 2019). "In CALM/AF10 leukemia, HOXA5 overexpression results from hDOTL1-dependent retention of CALM/AF10 in the nucleus and local H3K79 hypermethylation at the HOXA5 locus." (PMID 27588395, 2016). "In CALM/AF10 leukemia, HOXA5 overexpression results from CALM/AF10 recruitment of hDOT1L and local H3K79 hypermethylation at the HOXA5 locus, whereas a global reduction of this epigenetic marker also occurs." (PMID 27588395, 2016). "Mercaptopurine (purine antagonist) showed the strongest negative correlation in AML among the compounds analyzed, suggesting it might possess potential efficacy against HOXA5-driven leukemia." (PMID 41209012, 2025). "Knockdown of HOXA5 by siRNAs has been shown to overcome cytarabine resistance in leukemia cells." (PMID 34531456, 2021). "A study by Li and colleagues showed that HOXA5 knockout significantly inhibits the proliferation of AML cells, whilst shRNA down-regulation of HOXA5 may induce apoptosis and overcome drug resistance in leukemia cells." (PMID 31426381, 2019). "Thus, FLT3 expression was associated with HOXA5, HOXA7, HOXA9 and MEIS1 in human leukemia and this gene expression profile was confined to leukemia with either intermediate or unfavorable cytogenetics." (PMID 17712416, 2007). "Analysis of the selected Hox A cluster and Hox cofactor genes revealed a high degree of co-expression between these in leukemia samples, where correlation coefficient between HOXA5, HOXA7, HOXA9 and MEIS1 ranged between 0.83 and 0.92 (Spearman rank correlation, p<0.0001 in all cases)." (PMID 17712416, 2007). "Finally, we performed gene expression studies in MLL-AF9 and MLL-AF6 transformed bone marrow cells and found that genes highly relevant to MLL leukemia (Hoxa5, Hoxa9, Hoxa10, Meis1, and Mef2C) were expressed at much lower levels in the ΔSET Ash1l versus WT Ash1l cells." (PMID 33990599, 2021). "In addition, the upregulation of HOXA5 through H3K79 methylation may represent a potential mechanism for leukemia transformation via the CALM-AF10 fusion gene." (PMID 31426381, 2019). "Compared to levels in Hoxa9/Meis1 leukemias, endogenous Hoxa9 and Hoxa10 were considerably elevated in SQSTM1-NUP214 leukemias, whereas the levels of Hoxa3, Hoxa5, Hoxa7, Hoxa11 and Meis1 were comparable in Hoxa9/Meis1 and SQSTM1-NUP214 leukemias." (PMID 32343715, 2020). "As a potential lncRNA biomarker in leukemia, HOTAIRM1 was identified to activate the temporal collinear HOXA gene, including HOXA5." (PMID 31168296, 2019). "We identified differential methylation of genes that have been related to cancers such as lymphoma (WNT6, TP73, and CD37), leukaemia (MEIS1, HOXA4, and HOXA5) or neuroblastoma (TP73), as well as genes related to cardiovascular diseases (UCN, PRDM16, TCAP, ALOX5)." (PMID 35354948, 2022). "However, during leukemia, the abnormally high expression of FOXC1 in AML and the interaction between HOXA5/HOXA9, members of the Hox family, can lead to abnormal myeloid differentiation." (PMID 35504885, 2022). "In addition to local H3K79 hypermethylation at the HOXA5 locus, CALM/AF10-positive leukemia is characterized by a global reduction of the H3K79 epigenetic mark." (PMID 27588395, 2016).
leukemia (continued). "In addition HOXA5 expression is lost in breast tumors and HOXA genes, normally playing suppressor roles in leukemia development, are frequent targets for gene inactivation." (PMID 24148231, 2013). "However, their expression did not correlate with HOXA5, HOXA7, HOXA9 or MEIS1 and only weakly with PBX3 expression in human leukemia (Spearman, r = 0.37, p = 0.033 and r = 0.44, p = 0.078 respectively)." (PMID 17712416, 2007).
Obesity (13 papers, 2013 to 2025). Accumulation of substantial excess body fat. "The epigenetic dysregulation of the HOXA5 gene is associated with adipocyte hypertrophy in human obesity and contributes to adipose differentiation in mice." (PMID 37627406, 2023). "Accordingly, a positive association between DNA methylation in HOXA5 and BMI was reported in a Mexican American cohort, a population with a high prevalence of obesity." (PMID 37626900, 2023). "In this review, we integrate the current evidence about the involvement of HOXA5 in regulating AT function, as well as its association with the pathogenesis of obesity and T2D." (PMID 37626900, 2023). "Taken together, these results shed light on the mechanisms underlying Hoxa5‐dependent inhibition of obesity‐induced chronic inflammation by reducing ERS and promoting polarization of M2 macrophages." (PMID 31441588, 2019). "In summary, these findings revealed a novel mechanism that linked Hoxa5 to white adipocyte apoptosis, which provided some potential possibilities to prevent and treat obesity and some metabolic diseases." (PMID 29221131, 2017). "Thus, HOXA5 expression is related to the degree of central obesity and the pattern of body fat distribution and, by extension, should be associated with an increased risk for obesity-related abnormalities such as IR and T2D." (PMID 37626900, 2023). "Thus, an inappropriate HOXA5 gene expression may be a mechanism causing or maintaining an impaired AT function in obesity and potentially linking obesity to its associated disorders." (PMID 37626900, 2023). "Therefore, HOXA5 deficit may also affect multiple signaling pathways, commonly implicated in connecting obesity with an increased risk of cancer." (PMID 37626900, 2023). "Importantly, we identified four genes (CSN1S1, DMRT2, DMRT3 and HOXA5) as novel candidate genes of body fat distribution pattern in Africans, whose biological function and implication in the pathogenesis of obesity-associated metabolic diseases remain to be unravelled." (PMID 32581226, 2020). "Among the genes analyzed, HOXA5 was the most hypermethylated in patients treated with growth hormone, making it a strong candidate for a biomarker in the obesity process." (PMID 40564006, 2025). "An abnormal HOXA5 expression in the AT, caused in part by epigenetic dysregulation, may impair normal development and differentiation programs resulting in malfunction at the cellular and tissue levels, which are primary abnormalities in obesity and its related illnesses." (PMID 37626900, 2023). "Strikingly, HOXA5 is strongly downregulated in both visceral and SAT from individuals who have obesity, and its expression is inversely associated with both BMI and waist-to-hip ratio (WHR)." (PMID 37626900, 2023). "Given the growing body of evidence linking HOXA5 to the pathogenesis of obesity and T2D, a comprehensive review of its functions and mechanisms in regulating AT function is required." (PMID 37626900, 2023). "Its overexpression significantly suppresses invasive capability in lung cancer by reducing the expression levels of several actin remodeling-related genes, a finding that is in agreement with the role of HOXA5 in AT remodeling in obesity conditions." (PMID 37626900, 2023). "HOXA5 also ameliorates obesity-related inflammation and metabolic disturbance through its immunomodulatory function." (PMID 37626900, 2023). "The role of HOXA5 in the pathophysiology of metabolically unhealthy states such as AT hypertrophy, obesity, and T2D will be explored below." (PMID 37626900, 2023). "With respect to cardiometabolic traits, we found that HOXA5 was reported in an EWAS on obesity in African Americans, while OSR1 was reported in an EWAS on insulin resistance and T2D among European populations." (PMID 35836279, 2022). "This prompted us to explore the underlying relationships between Hoxa5, ERS and ATM polarization, thereby clarifying the role of Hoxa5 in the development of obesity and its regulatory mechanisms." (PMID 31441588, 2019).